FBLN1 (fibulin 1)
Diseases named in the same sentence as FBLN1 in open-access papers (continued):
Sharing a sentence is not in itself a finding about the gene and the disease.
tumor (79 papers, 2002 to 2025). "Mac Mrc1-enriched spots were enriched at the tumour periphery, and correlation analysis revealed a significant positive association between Mac Mrc1 and Meg3, Fbln1 and Lrrc15 CAF subtypes, which suggested proximity." (PMID 37605008, 2023). "The mutation of FBLN1 gene prevents the tumor cells from senescence, which conforms to their growth characteristics." (PMID 36404510, 2022). "Angiogenin has been implicated in tumor cell proliferation and was found to interact with extracellular matrix proteins, such as fibulin-1." (PMID 33802060, 2021). "For example, in addition to their well characterised roles in actin cytoskeleton dynamics, cofilin-1, fibronectin and fibulin-1 have also been implicated in cellular migration, tumour invasion and mitosis." (PMID 34832109, 2021). "Fibulin-1 is an extracellular matrix and plasma protein that has been implicated as playing a role in tumor progression." (PMID 25234557, 2014). "The finding that Fbln-1 expression is associated with improved survival in patients with lymphoid infiltrate at the tumor site suggests the possible involvement of Fbln-1 in triggering protective antitumor immune responses." (PMID 21113302, 2010). "Despite there being substantial evidence for fibulin-1 having the ability to influence tumour cell behaviour, there is a very limited understanding of the expression of fibulin-1 protein in association with human cancers." (PMID 12644824, 2003). "Clearly, additional investigations are required to determine if enhanced fibulin-1 protein expression is associated with other tumour types and if such altered expression is variant-specific." (PMID 12644824, 2003). "Fibulin-1 is an extracellular matrix and plasma protein that has been implicated as playing a role in tumour progression." (PMID 12644824, 2003). "Among them, FBLN1 is closely associated with tumor cell migration, adhesion, and invasion." (PMID 38441550, 2024). "Fibulin 1 is also a plasma protein capable of binding to fibrinogen and may play a role in hemostasis and thrombosis; moreover, it is implicated in tumor formation and invasion processes as a tumor suppressor." (PMID 34357026, 2021). "Although a global increase of FBLN-1 is associated with tumor cells, the FBLN-1 isoforms may have distinct, important roles in regulating cellular behavior." (PMID 20967215, 2010). "Furthermore, Fibulin-1 is associated with tumor development." (PMID 32612994, 2020). "The tumor-suppressing effect of fibulin-1 has been reported for many types of cancers, including gastric, prostate, and estrogen-dependent cancers." (PMID 41301725, 2025). "Fibulin-1 is a calcium-binding plasma and extracellular matrix (ECM) protein that has been implicated in cellular transformation and tumour invasion." (PMID 38921769, 2024). "CTSF and AKR1B10 staining were notably dominant in the cytoplasm of tumour cells while FBLN1 staining was also observed in the interstitial cells in addition to the cytoplasm of tumour cells." (PMID 35217799, 2022). "Some other studies have also reported that fibulin-1 expression is significantly upregulated in some cancers, validating its role in promoting tumor occurrence and development." (PMID 36034715, 2022). "The glycoprotein fibulin-1 seems to possess both tumor suppressive and tumor enhancing effects, as revealed from various studies." (PMID 34063320, 2021). "The area under receiver operating characteristic curves (AUC) was 0.791 for Fibulin-1, 0.640 for α-fetoprotein and 0.868 for the combination of the two tumor markers." (PMID 32612994, 2020). "In various aspects of tumor cells, such as cell motility, cell proliferation, apoptosis, and angiogenesis, fibulin-1 (FBLN1) was reported as a novel ECM protein." (PMID 33613617, 2020). "FBLN1 (Fibulin1) plays a role in cell adhesion and migration, and has been classified as potential tumor suppressor gene because of its capacity to suppress fibronectin-mediated inhibitory effects on cell attachment and spreading." (PMID 32974182, 2020).
tumor (continued). "Further, overexpression of FBLN1D in fibrosarcoma cells is seen to inhibit tumor growth in vivo, with purified placental FBLN1 seen to inhibit adhesion, spreading, motility and invasion of breast cancer cells." (PMID 32719793, 2020). "As a tumor suppressor FBLN1 levels are downregulated in epithelial cancers including melanoma, squamous cell carcinoma, renal cell carcinoma, hepatocellular carcinoma, gastric carcinoma, prostate carcinoma, colorectal carcinoma, and lung adenocarcinoma (LUAD)." (PMID 32719793, 2020). "It was reported promoter hypermethylation of Fibulin-1 was related to tumor progression in HCV-related HCC." (PMID 32612994, 2020). "Like fibulin-1, ADAMTS-1 has also been implicated to participate in tumor processes with a dual function." (PMID 31508361, 2019). "In relation to tumor processes, fibulin-1 shows a dual function, since both oncogenic and tumor-suppressive properties have been described for this protein." (PMID 31508361, 2019). "Immunostaining of the mCAF markers Fibulin-1 and PDGFRα showed high prevalence of positive cells at the invasive front of tumors, in contrast to the relatively low abundance of mCAFs in the tumor core." (PMID 30514914, 2018). "Immunohistochemical analysis and qRT-PCR analysis showed that FBLN1 protein and messenger RNA (mRNA) levels in tumor tissues were both significantly decreased compared with that in adjacent nontumor tissues." (PMID 25837757, 2015). "The results showed that the CpG sites were highly methylated in tumor tissues for FBLN1, and the methylation level varied from 30% to 77.2%, with a mean ratio of 61.54% in the tumor tissue." (PMID 25837757, 2015). "As a novel ECM protein, fibulin-1 had been reported a multifunction protein in variable aspects of tumor cells, such as cell motility, cell proliferation, apoptosis and angiogenesis." (PMID 25234557, 2014). "BEX1 and FBLN were associated with ER, while FBLN1, HBEGF, KLK3, and TMPRSS2 were associated with tumor aggressiveness." (PMID 21134280, 2010). "The peak identified by standard includes FBLN1, a gene that has been previously selected as candidate tumor suppressor." (PMID 20398270, 2010). "Since PC is characterized histopathologically by prominent fibrosis in the tumor microenvironment, decreased expression of fibulin-1 might be useful marker not only for detecting PC but also for reflecting the degree of fibrosis in PC." (PMID 41301725, 2025). "Even more, Kaplan-Meier survival curves of progression-free survival (PFS) demonstrated inferior survival probabilities in patients with high tumor expression of PXDNL (p=0.0001) and SDC1 (p<0.0001) and low tumor expression of FBLN1 (p=0.0087), FBLN5 (p=0.026) and ADAMTS8 (p<0.0001)." (PMID 37056938, 2023). "Four of 13 overlapped markers (MXRA8, CLMP, VCAN and FBLN1) are involved in cell adhesion and tumor metastasis, suggesting that dysfunctions in cell adhesion pathways could lead to anti-PD-1 resistance associated by RIPK1 and AXL." (PMID 36518525, 2022). "Hence, fibulin-1 plays a dual role in promoting and suppressing the progression of the tumor, depending on the cell types; however, an in-depth study is needed to understand the mechanisms." (PMID 34063320, 2021). "FBLN1 is closely related to migration, adhesion, and invasion of tumor cells." (PMID 33602229, 2021). "These proteins (THBS1, FBLN1, EDIL3, QSOX1, ACTN4, MMP3) also displayed differential mRNA expression in CRC compared to healthy intestine in the CRC TCGA dataset, and are implicated in tumour growth and metastasis regulation." (PMID 33802764, 2021). "Moreover, the protein level of Fibulin-1 was also significantly increased in HCC tissues compared with that in adjacent non-tumor liver tissues, as shown in the western blot analysis." (PMID 32612994, 2020). "Fibulin-1 is seen to exhibit both pro-oncogenic as well as tumor suppressive effects." (PMID 32719793, 2020).
tumor (continued). "Upregulation of Fibulin-1 expression may confer malignant transformation and promote tumor progression, suggesting a potential application for Fibulin-1 silencing in anticancer therapy." (PMID 32612994, 2020). "Furthermore, it is remarkable that the elevation of tumor purity (i.e., the percentage of cancer cells in a solid tumor sample) was negatively correlated with the expression of FBLN1 by using the TIMER web server." (PMID 32612994, 2020). "The silencing of Fibulin-1 in BEL-7402 cells significantly reduced the tumor volume." (PMID 32612994, 2020). "FBLN1 was observed to significantly down-regulated in RCC cell lines and patient tissues through promoter hypermethylation, and FBLN1 over expression led to decreased cell growth, enhanced tumor cell apoptosis, decreased cell motility, and angiogenesis of RCC cells in vitro and in vivo." (PMID 33542901, 2020). "Fibulin-1 is known to possess both tumor suppressive and enhancing effects." (PMID 30227601, 2018). "FBLN1 is a secreted glycoprotein that is found in association with ECM structures including fibronectin and elastin containing fibers and basement membranes and it has been implicated in cellular transformation and tumor invasion." (PMID 28333958, 2017). "Also in HCC, the promoter hypermethylation of FBLN1 has been described and shown to be associated with reduced expression of FBLN1 mRNA, advanced stage HCC, multiple tumors and increased tumor size." (PMID 28333958, 2017). "Fibulin 1 (FBLN1) is down regulated in a number of tumours, including prostate." (PMID 27124473, 2016). "The results showed that the FBLN1 promoter was hypermethylated in tumor tissues." (PMID 25837757, 2015). "However in the development of hepatocellular carcinoma, gastric cancer and prostate cancer, fibulin-1 demonstrated tumor-suppressive activity, suppressing tumor growth, enhancing cell apoptosis and inhibiting tumor angiogenesis." (PMID 24236050, 2013). "In addition, promoter methylation was frequently detected in tumour samples but not in adjacent non-tumour and normal gastric tissue samples, highlighting a tumour-specific hypermethylation of the FBLN1 promoter." (PMID 18985039, 2008). "It is tempting to propose that the balance of fibulin-1 variant expression is an important determinant of whether the expressed fibulin-1 displays tumour-suppressive or oncogenic activities." (PMID 12644824, 2003). "In addition, we observed no significant alteration in the expression of the 55 kDa processed form of fibulin-1 between normal- and tumour-derived breast tissue." (PMID 12644824, 2003). "Additionally, COL1A1 and FBLN1 were previously used as markers for canine tumor or fibroblast cells, and MMP2 and DCN as markers of mesenchymal-like cells in human cancers, with the latter also being a top differentially expressed gene in our canine STS sample." (PMID 41208961, 2025). "Therefore, FBLN1 may be involved in regulating the various stages of BM of tumour cells, such as detachment from the primary tumour, infiltration of blood vessels, and colonisation of the brain parenchyma." (PMID 35217799, 2022). "FBLN1 and ANT3 might be potential tumor- and HPV-associated serum markers." (PMID 33602229, 2021). "Thus, tumor cells may upregulate Fibulin-1 expression to survive in the harsh environment, emphasizing the potential of Fibulin-1 as a relevant target in the tumor microenvironment." (PMID 32612994, 2020). "Current data indicate that FBLN1 might have a tumor suppressive function." (PMID 25234557, 2014). "Importantly, loss of fibulin-1 expression was associated with tumor grade (P < 0.05), but not with other clinicopathological parameters such as age, sex or tumor stage (P > 0.05)." (PMID 25234557, 2014). "Therefore, speculation stillexists regarding FBLN1 as a tumor-suppressor gene or an oncogene orit might even have dual functions." (PMID 21079744, 2010). "Current data indicate that FBLN1 might have a tumour suppressive function." (PMID 18985039, 2008).
tumor (continued). "Network visualization highlighted key gene hubs involved in these processes, including FBLN1, CAV1, FGFR4, and ITGB1, suggesting a possible role for TNBC epithelial cells in modulating the tumor immune microenvironment." (PMID 41595458, 2025). "CAFs can also secrete numerous cytokines, such as ACTA2, FBLN1, TAGLN, etc., remodeling the tumor extracellular matrix, thereby leading to tumor progression." (PMID 38755647, 2024). "All six proteins are differentially expressed in malignant vs. healthy tissue in CRC (FBLN1, MMP3, ACTN4, THBS1, EDIL3) or other tumour entities (QSOX1)." (PMID 33802764, 2021). "By contrast, SEMA4B, KRT1, KRT9, FBLN1, and PTGDS are involved in the anti-invasive activity of tumor cells." (PMID 32953262, 2020). "The collagen family (COL1A2, COL1A1, COL6A3, and COL5A1), DCN, FBLN1, and POSTN were the most abundant components of the tumor ECM." (PMID 33613617, 2020). "As cfDNA can in principle originate from different tissue and organ locations, we also sought to analyze FBLN1 and VIM methylation in liver tissues, including HCC tissue and adjacent non-tumor tissues, of patients recruited in the French series." (PMID 28333958, 2017). "FBLN1 and VIM methylation was also studied in liver tissues (including HCC tissue and paired adjacent non-tumor tissue) from separate nine cases from the French case series." (PMID 28333958, 2017). "Among these were several genes with known tumour suppressor activity (e.g. FLNA, FBLN1, MYL9, CLIC4 and SEC23A)." (PMID 27124473, 2016). "FN1 functionally connects a pair of coexpressed glycoproteins, FBLN1 and FSTL1, and SPARC is connected to IGFBP7, a tumor suppressor, which creates a functional link between a candidate tumor suppressor, PDGFRL, and a mesenchymal factor, FSTL1." (PMID 24944582, 2014). "Some proteins from this list have also been identified in tumor studies as clinical outcome predictors (NOV, CLU TNC, POSTN, IGFBP2, LCN2) or mediators of resistance to chemotherapy (CLU, FBLN1, THBS, STIP1, PTGES3, IGFBP4, ATOX1)." (PMID 19936259, 2009). "However, we could not find any significant association of FBLN1 promoter methylation with clinical characteristics, including age, gender, H. pylori infection, tumour grade, Lauren classification and differentiation." (PMID 18985039, 2008). "Furthermore, the ratio of the 50 kDa fragment to the mature fibulin-1 polypeptide correlated with the level of oestrogen receptor α (Spearman correlation coefficient, rs=0.49, P<0.003, n=36) and progesterone receptor (rs=0.43, P=0.008, n=36) expression in the tumour specimens." (PMID 12644824, 2003). "In this sense, Matrigel showed a higher amount of Fibulin-1 and LAMA5 laminin subunit, two components previously related to the inhibition of tumor progression processes because they mediate different cell attachment, migration, and organization processes into tissues." (PMID 36059712, 2022). "Moreover, Nutlin also regulated the tumor-promoting HSF1 targets CDC6, ITGB3BP, RBBP5, BST2, and FBLN1." (PMID 34188043, 2021). "First, we detected the expression of different Fibulin-1 transcripts in each tumor and non-tumor pair using a real-time PCR analysis, and then the tumor-to-non-tumor ratios of Fibulin-1 expression were calculated." (PMID 32612994, 2020). "However, when we checked the expression of several tumor less aggressiveness-related genes, such as ACTA2, FBLN1, F2R, we found that the expressions of these genes were increased upon overexpression of PAGE4." (PMID 30658679, 2019). "More precisely, FLNA FBLN1, MYL9, CLIC4 all have demonstrated tumour suppressor activity." (PMID 27124473, 2016). "We measured the expression of FBLN1 by immunohistochemical analysis in 68 pairs of tumor and adjacent nontumor tissues." (PMID 25837757, 2015).
tumor (continued). "The expression levels of FBLN1 protein were significantly downregulated in tumor tissues compared with nontumor tissues." (PMID 25837757, 2015). "Fibulin 1 expression was significantly downregulated in most of the tumour tissues compared with adjacent non-tumour tissues." (PMID 18985039, 2008). "Fibulin-1 protein expression and processing did not correlate with any other prognostic variables, including tumour size, histological type, tumour stage or lymph node involvement." (PMID 12644824, 2003). "We examined the expressions of CTSF, FBLN1 and AKR1B10 in BM tissues of 47 patients with NSCLC BM using IHC (cohort 3); 10 of these patients underwent orthotopic tumour excision in the early stages of the disease and the corresponding primary tumour tissues were also obtained." (PMID 35217799, 2022). "The mCAF subset of the tumor stroma specifically expressed transcripts of a large variety of ECM-related genes, such as glycoproteins (Dcn, Lum, and Vcan), structural proteins (Col14a1), matricellular proteins (Fbln1, Fbln2, and Smoc), and matrix-modifying enzymes (Lox and Loxl1)." (PMID 30514914, 2018). "Most of the validated mRNAs provided unique information about tumor aggressiveness, however, three pairs of transcripts in the validated set of 23 were correlated (P‐values < 0.05): CCNA2 and TPX2 (r2 = 0.61); SRD5A2 and DPT (r2 = 0.56); and SRD5A2 and FBLN1 (r2 = 0.73)." (PMID 28145099, 2017). "Hence, fibulin-1 could potentiate degradation of ECM components by ADAMTS-1 and thereby facilitating tumor progression." (PMID 24457941, 2014).